IL6 (interleukin 6)
Diseases named in the same sentence as IL6 in open-access papers (continued):
Sharing a sentence is not in itself a finding about the gene and the disease.
tumor (continued). "IL-6 is secreted by tumor cells to regulate tumorigenesis and progression in two ways: it binds to IL-6 receptors (IL-6R) on its own target cells through the autocrine pathway, and it acts on IL-6R on the surface of other cells through the paracrine pathway." (PMID 37576403, 2023). "Previous research has tested other molecular markers, including tumour mutation burden (TMB), CD8+TiL and IL-6, but the prediction of pCR after neoadjuvant immunotherapy remains poor." (PMID 37583698, 2023). "Once IL-6 binds to its receptor on the plasma membrane of tumor or stroma cells, the pathway JAK1/STAT3 is activated and controls genes involved in proliferation, survival, invasion and metastasis formation." (PMID 36639824, 2023). "Interleukin-6 (IL-6) plays a role in hormone release, tumor growth and proliferation, and the production of angiogenic factors, particularly vascular endothelial growth factor-A (VEGF-A)." (PMID 38275385, 2023). "Increased levels of IL-6 have been evidenced in patients with several tumor types, highlighting the link between inflammation and cancer." (PMID 37275882, 2023). "Interleukin 6 (IL-6) and growth factors in inflammatory and tumor cells can induce STAT3 activation, leading to cell proliferation and prolonged survival." (PMID 37631318, 2023). "The proliferation and anti-apoptotic potential of tumor cells are also attributed to the elevated levels of IL-6, IL-1b, and TNF-α." (PMID 36840009, 2023). "BA, BE, and its derivatives seem to cover all the potential complications of IL-6/IFNγ interplay in the tumor microenvironment." (PMID 36282372, 2023). "Our data demonstrate the implication of SOX2 in promoting DNA damage and genome instability by sustaining inflammation via FOSL2/IL6, resulting in tumor aggressiveness." (PMID 36932385, 2023). "Lack of SIRPα inhibited LLC cells growth in KO mice, associated with reduced infiltrating PD‐1+CD8+ T cells and production of IL‐6 from infiltrating macrophages and neutrophils in tumour tissues." (PMID 36419386, 2023). "Specifically, STAT4 overexpression was correlated with an increased abundance of CAFs within the tumor microenvironment that was further accompanied by increased concentrations of CAF-secreted factors IL6, CXCL12, and VEGFA." (PMID 37173951, 2023). "IL-6 is secreted not only by cancer cells, but also from stromal cells in the tumor microenvironment." (PMID 36675246, 2023). "In OC, IL-6 secretion by MSC induced tumor cells’ expression of Bcl-2 and Bcl-XL, as well as consequent apoptosis inhibition." (PMID 37175439, 2023). "Human interleukin-6 (IL-6) is secreted by T-cells, B-cells, monocytes, macrophages, fibroblasts, keratinocytes, endothelial cells, mesangial cells, adipocytes and some tumor cells." (PMID 37812611, 2023). "The nuclear factor κB/IL-6/STAT3 cascade is an important regulator of these effects in tumor-initiating intestinal epithelial cells." (PMID 36572816, 2023). "Alternatively, cytokines such as IL-6, IL-17, and IL-23 have been reported to enhance tumor progression." (PMID 37893013, 2023). "IL-6 is a key mediator of multiple cellular processes regulating tumor growth and treatment resistance." (PMID 37696858, 2023). "IL-1β is known to enhance proinflammatory and anti-tumor effects and help the recruitment of immune cells, and IL-6 can be produced by various immune cells and shows both proinflammatory and anti-inflammatory roles according to the surrounding environment." (PMID 37242761, 2023). "Overactivation of KRAS signaling has been shown to enhance the secretion of interleukin-6, which is necessary for tumorigenesis and tumor development." (PMID 37457560, 2023). "Among the eleven immunological markers examined, three (PD-L1, TNF-α, and IL-6) demonstrated a decline in the proportion of tumors with a high marker expression in late-stage compared to early stage tumor samples." (PMID 37444550, 2023).
tumor (continued). "IL-6 was the only cytokine in the tumor lysate that significantly changed its concentration (p < 0.05) after treatment with 6.25; 12.5 and 25 mg/kg of H. junceus scorpion venom, compared to the untreated group." (PMID 38137888, 2023). "Dendritic cells and macrophages of the tumor microenvironment are hyperactivated and secrete high levels of IL-6, an agent with pro-inflammatory and pro-proliferative activity on the TFH malignant clone." (PMID 37182145, 2023). "In head and neck cancer (HNC), CAF-secreted IL-6 induces the expression of osteopontin and promotes tumor invasion and metastasis through the integrin αvβ3-NF-kappa B signaling pathway." (PMID 37217855, 2023). "These genes included those related to P/DAMP signaling (e.g., Il6, Tlr1, Tlr4, Il1b, Il18), necroptotic tumor cell death (e.g., Casp1, Casp8, Il1b), and activation of the adaptive immune system (e.g., Cd80, Cd8a, Ccr5, Cxcl10)." (PMID 37213298, 2023). "IL-6 secreted by tumor-stimulated BMMSCs, enhances the stemness and migration capacity of osteosarcoma cells." (PMID 37885883, 2023). "Suppression of IL6/JAK1-mediated PD-L1 glycosylation sensitized anti-Tim3 immune checkpoint blockade (ICB) therapy as manifested by reduced tumor growth and prolonged survival in Hepa1-6 hepatoma-bearing mice." (PMID 37193819, 2023). "IL‐6 expression is abnormal only when an inflammatory reaction occurs or there is a tumor, and it participated in multiple cellular functions." (PMID 37904699, 2023). "This phenomenon increases the immunogenicity of the tumor microenvironment once DAMPs induce the maturation of DCs, and pro-inflammatory cytokines, such as IL-2, IL-6, IL-12, INF-γ and TNF-α, were also reported to increase." (PMID 37238966, 2023). "Module 11 was enriched in acute-phase response signaling, the tumor microenvironment pathway, and IL-6 signaling." (PMID 36985953, 2023). "By secreting CCL-2, IL-6, and CXCL8, FAP+ CAF-like cells are able to induce macrophages differentiation into tumor-associated macrophages." (PMID 37166418, 2023). "In our prior bulk microarray analysis, we showed enrichment of the IL-6/STAT3 pathway in EPN tumor flow-sorted myeloid cells." (PMID 37694144, 2023). "This last type of microenvironment is common in tumors, and it is characterized by the presence of IL-10 and IL-6, which favors tumor proliferation and metastasis." (PMID 37283734, 2023). "For example, there is evidence that bone marrow MSCs promote the formation of MM by secreting interleukin-6 (IL-6) as a tumor cell growth factor." (PMID 37745073, 2023). "The tumor-promoting effects of IL-17 and its receptor IL-17R are achieved through direct influence on tumor cells via the IL-6/JAK2/STAT3-related pathway." (PMID 37762066, 2023). "In PDAC, effects of CAFs on tumour cells include increased proliferation, migration and invasion, for instance via indirect interleukin (IL)-6 signalling." (PMID 37240052, 2023). "The IL-6 promotes tumor angiogenesis and reduces inter-tumor cell adherence; it inhibits the body’s anti-tumor immunity; it also has anti-apoptotic effects, thus promoting tumorigenesis." (PMID 36983320, 2023). "This XIST-driven production of IL-6 from ALDH− bulk tumor cells preferentially binds to IL6R on ALDH+ CSCs to drive STAT3 activation and expression of key CSC factors (i.e., c-MYC, KLF4 and SOX9), promoting self-renewal of ALDH+ CSCs." (PMID 36922677, 2023). "Three of these cytokines (IP-10/CXCL10, IL-6, and PDGF-AA) were also among those consistently associated with the tumor dimensions in all—current and previous—vitreous studies of UM." (PMID 37509362, 2023). "The activity of mast cells against tumours is regulated by interleukin-6, −8 and −10 (IL-6, IL-8 and IL-10) and chemokine ligands 3 and 5 (CCL3 and CCL5)." (PMID 37928785, 2023). "They observed that inhibiting ERK5 activity or depleting ERK5 expression prevented IL-6 production in tumor cells." (PMID 37601096, 2023).
tumor (continued). "Trans-signaling of IL-6 can enhance CD8+ T cell trafficking to the tumor, while also decreasing Treg presence and IL-6 produced from dendritic cells (DCs) can increase T cell survival." (PMID 37461742, 2023). "In physiological conditions, the activity of IDO-1 is minimal, but it is highly induced by the following: interferons γ, α, and β; bacteria lipopolysaccharides; viruses; proinflammatory interleukins (IL-1, IL-6, and IL-8); and tumor cells." (PMID 36980311, 2023). "We measured human and mouse IL-6 levels in plasma to figure out if IL-6 was specifically produced by the human L3.6pl tumor cells or mouse immune cells." (PMID 36672405, 2023). "First, tumor cells have been observed to secrete high levels of IL-6, which upregulate the expression of the IL-6 receptor (IL-6R) in MSCs while enhancing their proliferation and migration towards the tumor both in vitro and in vivo." (PMID 36830980, 2023). "GCMSCs efficiently promote macrophage polarization toward the pro-tumor M2 subtype through several soluble molecules, including IL-6, IL-8, TGF-β, HGF, PGE2, IL-1RA, TSG6 and IDO." (PMID 37885883, 2023). "LITs were found to significantly increase the expression of IL-6 in both peripheral blood and targeted tumor within hours postoperatively, however, incomplete LITs showed a higher and prolonged expression of IL-6 than did complete LITs." (PMID 36831664, 2023). "In tumor‐bearing mice, blockade of IL‐6 promoted the infiltration of CD8+ T cells and IFN‐γ+CD4+ T cells and sensitized anti‐PD‐1 therapy." (PMID 38020717, 2023). "CAFs play a tumor-promoting role in esophageal carcinoma through IL-6- and CCL2-promoted tumor migration and TAM-like polarization and invasion of macrophages." (PMID 37046676, 2023). "Tumour cells directly synthesize fibrinogen and produce interleukin-6 to stimulate fibrinogen secretion, leading to tumour progression and metastasis." (PMID 38031022, 2023). "On the other hand, activated fibroblasts release Interleukin-6 (IL-6), which increases tumor-cell invasiveness and chemoresistance." (PMID 37173963, 2023). "Inflammatory cytokine IL-6 is another important inflammatory cytokine, and it is closely related to inflammation and tumor." (PMID 36874003, 2023). "In summary, CD90+ fibroblasts are involved in tumor cell progression through the IL-6, PI3K/Akt and MAPK pathways." (PMID 36747131, 2023). "Increased levels of IL-6 in the tumour microenvironment and/or mutations of loss-of-function mutations affecting STAT3 negative regulators result in STAT3 hyperactivation in tumour cells." (PMID 37753372, 2023). "On the other hand, IL‐6 is predominantly expressed by M2 cells in the later phase of inflammation and tumour development, it exerted anti‐inflammatory and pro‐tumour effects, respectively." (PMID 36419386, 2023). "IL-6, a pro-inflammatory cytokine that shows diverse functions of cell multiplication, injury, infection, and inflammation, affects tumor cells to develop PC by controlling vascular endothelial growth factor (VEGF) secretion." (PMID 36899319, 2023). "M1-like macrophages inhibit tumor growth and facilitate cancer therapy via secreting chemokines, such as interleukin 6 (IL6) and tumor necrosis factor α (TNFα), whereas M2-like macrophages promote tumor growth." (PMID 37849457, 2023). "Likewise, a fully controlled response may be associated, for instance, with the counteraction of tumor-induced cachexia and the inhibition of catabolic pathways (IL-6, TNF-alpha) balanced with the stimulation of anabolic pathways (FoxO3a, p-AKT, p-mTOR, and P-GSK-3β)." (PMID 37895979, 2023). "M1 macrophages mainly induce the production of pro-inflammatory cytokines such as TNF-α, IL-1β, IL-6, and IL-12, which are conducive to anti-tumor effects." (PMID 37758759, 2023). "Whereas among pro-inflammatory cytokines, recent evidence suggests that IL-6 is a central role linking chronic inflammation to cancer, by driving tumor initiation and subsequent growth and metastasis." (PMID 37430251, 2023).
tumor (continued). "Meanwhile, exosomal miR-101 also affects macrophage function by suppressing IL1A and IL6 expression, which reduces growth and macrophage tumor infiltration in vivo." (PMID 38002256, 2023). "For example, IL-6 or tumor-related factors can induce the overexpression of lnc C/EBPβ, LNC-CHOP, Olfr29-ps1, Pvt1 and RNCR3 in MDSCs, while chronic and low-dose stimulation of inflammation and tumor factors can also promote the down-regulation of lncRNAs." (PMID 36817434, 2023). "Within the TCGA LUAD cohort, tumor IL-6 expression strongly correlated with the adenosine signature (R=0.65; p<2.2e−16)." (PMID 37852738, 2023). "First, adipocytes can support the survival and growth of tumor cells by secreting various cytokines, adipokines, and growth factors, such as IL-6 and leptin." (PMID 37345073, 2023). "We focussed on endoglin, enolase γ, VEGF, IL‐6 and CCL20 which were all enriched in TSC2‐ EVs, compared to TSC2+ EVs, due to known associations with tumour‐promoting functions." (PMID 37337371, 2023). "IL-6 is a cytokine that acts on chronic inflammation as a major tumor-promoting inflammatory mediator." (PMID 37047012, 2023). "Serum levels of IL-6 correlated with the tumor stage of the RCC and was therefore considered a prediction factor of disease recurrence, progression, and OS and disease-specific (DS) survival." (PMID 37190141, 2023). "IL-6 signaling promotes tumor EMT, metastasis and invasiveness, which is thought to be a promising target for cancer treatment." (PMID 37047623, 2023). "Growing embodies showed that IL1, IL6, and TNFα are critical drivers of tumor growth, progression, and metastatic spread." (PMID 38213319, 2023). "IL6, a proinflammatory cytokine produced in tumor-bearing states, promoted in CRC growth, EMT and metastatic spread in association with dysfunctional antitumor immunity." (PMID 37686695, 2023). "Accumulating evidence shows that interleukin-6 (IL-6) promotes tumor invasion and migration in EOC, although the molecular mechanisms remain to be fully elucidated." (PMID 36814597, 2023). "IL-6 is commonly expressed by cancer stem cells (CSCs) and is strongly correlated with both tumor stage and poor prognosis." (PMID 38137547, 2023). "Recently, it was reported that inhibiting the SREBP pathway prevents HCC by downregulating tumor-promoting cytokines, including IL-6, TNF-α, and IL-1β." (PMID 37434430, 2023). "In inflammatory TME, IL-6 secreted by TAMs resulting in a vicious cycle that further promote macrophages polarization to TAMS and increase IL-6 expression which can lead to a smoldering inflammatory state, and enhance tumor cell metastasis." (PMID 36816959, 2023). "In normal tissues, Se-PC promotes the synthesis of antioxidant enzymes and the immune response by the IL-6/TNF-α pathway against tumor proliferation and metastasis." (PMID 37994159, 2023). "IL-8 promotes myeloid-derived suppressor cell recruitment to the tumor, while IL-6 activates the JAK/STAT pathway—a key hub of tumor-mediated immune suppression." (PMID 37509316, 2023). "IL-1β and IL-6 are cellular inflammatory components, and these factors modify the perivascular endothelial cell surroundings and promote tumor development." (PMID 36976205, 2023). "M1 macrophages induced by cytokines, such as transforming growth factor (TGF)-β, interleukin (IL)-6, and IL-10, have anti-tumor activity." (PMID 36693070, 2023). "Of these, 21 proteins were enriched in TSC2‐ EVs, with IL‐6, MMPs, VEGF, Galectin‐3 previously associated with mTORC1‐driven tumours." (PMID 37337371, 2023). "Functional studies have shown that PFA1 tumor cells reprogram myeloid cells to a myeloid-derived suppressor cell (MDSC)-like phenotype through an NF-κB/IL-6/STAT3 signaling pathway." (PMID 37694144, 2023). "In contrast, tumor-derived soluble factors M-CSF, IL-6, IL-1β, IL-4, IL-10, CCL2 initiate the immunosuppressive pathways that commit immature myeloid cells to become MDSCs and further promote the differentiation towards M-MDSC." (PMID 38304256, 2023).
tumor (continued). "Via NF-κB pathway blockade, the expression of IL-6 in splenic MDSCs was significantly reduced after cryo-thermal therapy compared with that in tumor-bearing mice." (PMID 37108179, 2023). "In both cases, cytokines such as interleukin-6 (Il-6) influence tumor genesis and Il-6 also plays a role in tendon ruptures." (PMID 37563331, 2023). "CRP is an acute-phase reactant that is mainly produced by hepatocytes under the influence of proinflammatory cytokines, particularly interleukin-6 (IL-6), which are commonly over-produced in cancer cells and immune cells that infiltrate tumor tissue." (PMID 37509622, 2023). "Previously, we reported that CAF elimination suppresses tumor growth and neutralizing local Interleukin-6 (IL-6) in the TME secreted by CAFs improves tumor immunosuppression." (PMID 36764954, 2023). "The increase in M2 macrophages was associated with increased levels of interleukin (IL)‐6 and prostaglandin E2 (PGE2), two inflammatory mediators known to skew the differentiation of monocytes to tumor‐promoting M2 macrophages." (PMID 37208929, 2023). "M1 macrophages produce various pro-inflammatory cytokines, such as tumor necrosis factor-alpha (TNF-α), interleukin-1 beta (IL-1β), and interleukin-6 (IL-6), which have been shown to inhibit tumor growth." (PMID 37999824, 2023). "Accordingly, TGF-β1, IL-10 and CCL2 protein levels were significantly increased, and TNFα, IL-6, IL-1β and IL-12p40 protein levels were significantly decreased in tumor tissues in mice with MO-Mettl3 macrophages compared with mice with MO–nc macrophages." (PMID 37402945, 2023). "Release of cytokines such as TNF-α and IL-6 following NF-κB activation activates pro-survival signals in tumor cells and promotes growth and progression." (PMID 37005447, 2023). "Among them, M1-type macrophages under stress have strong antigen-presentation ability and can secrete a large number of pro-inflammatory cytokines, such as TNF-α, IL-6, and IL-12, which have killing effects on tumor cells." (PMID 36903383, 2023). "Within the tumour microenvironment and in the periphery, IL-6 promotes differentiation of myeloid precursors into MDSCs and reinforces their suppressive function by promoting and maintaining STAT3 phosphorylation." (PMID 36161514, 2023). "Stroma cells produce miR-214 upon tumor cell signals which involve the activation of the IL-6/STAT3 signaling." (PMID 36639824, 2023). "After a literature review, we collect factors that directly regulate the function of NK cells, and the gene list is IL2, IL15, IL18, IL21, all of which promote NK cell-mediated tumor death, while IL6, TGFβ and TNFα promote NK cell exhaustion." (PMID 38159250, 2023). "HNSCC tumor cells produce IL-6, CXCL8, and EGF, which improve the survival and angiogenic potential of endothelial cells through the activation of the STAT3/AKT/ERK signaling pathways." (PMID 38003931, 2023). "Factors such as IL-8, VEGF, PDGF, NGF, SCF, and histamine promote tumor growth, while IL-1, IL-6, TNF-α, and fibroblast proteases inhibit tumor growth." (PMID 37686677, 2023). "In HNSCC, elevated MDSC levels have been reported to upregulate inflammatory mediators, such as IL-6, rendering the ecosystem unfavorable for antigen-presenting cell maturation and thus indirectly promoting tumor cell growth." (PMID 37024932, 2023). "TME enhances the tumor survival pathway by secretion of fibroblast growth factor, hepatocyte growth factor, interleukin-6, and transforming growth factor-β." (PMID 37509281, 2023). "We also evaluated the impact of the pathomorphological status of tumours on the level of IL-6 and IL-8 expression." (PMID 37047238, 2023). "IL-6 is a TAM-produced cytokine that is involved in tumor progression and metastasis through the STAT3 signaling pathway and is responsible for the prosurvival adaptation of tumor cells to hypoxia." (PMID 36838713, 2023).